Y_RNA (Y RNA )
Gene: Miscellaneous RNA gene on chromosome 15 (52,162,751 to 52,162,852, forward strand). Ensembl gene ENSG00000206995.
Homologues: Orthologues: chimpanzee Y_RNA (98% identical), macaque Y_RNA (97% identical), guinea pig Y_RNA (93% identical). Paralogues in human: RNY3 (93% identical), Y_RNA (93% identical), Y_RNA (92% identical), Y_RNA (91% identical), RNY3P1 (90% identical), Y_RNA (90% identical), RNY3P14 (89% identical), Y_RNA (89% identical), Y_RNA (88% identical), Y_RNA (87% identical), RNY3P16 (86% identical), RNY3P5 (86% identical), and 97 more.